PITPNC1 (phosphatidylinositol transfer protein cytoplasmic 1)
Description:
[Isoform 1]: Catalyzes the transfer of phosphatidylinositol (PI) and phosphatidic acid (PA) between membranes. Binds PA derived from the phospholipase D signaling pathway and among the cellular PA species, preferably binds to the C16:0/16:1 and C16:1/18:1 PA species. [Isoform 2]: Catalyzes the transfer of phosphatidylinositol between membranes.
Synonyms: MrdgBbeta; RDGBB1; RDGBB; RDGB-BETA; M-RDGB-beta
Tractability: PROTAC: ubiquitination databases record sites on it; its protein half-life has been measured.
Gene: Protein-coding gene on chromosome 17 (67,377,281 to 67,697,256, forward strand). Ensembl gene ENSG00000154217.
Subcellular location: Cytoplasm, cytosol
Subcellular location (Human Protein Atlas): Cytosol; Nucleoplasm
Gene Ontology:
Molecular function: phosphatidic acid binding; phosphatidic acid transfer activity; phosphatidylcholine transporter activity; phosphatidylglycerol binding; phosphatidylinositol binding; phosphatidylinositol transfer activity; phospholipid transfer activity; protein binding
Biological process: 1-phosphatidyl-1D-myo-inositol 4,5-bisphosphate biosynthetic process; phospholipid transport; signal transduction; intermembrane lipid transfer
Cellular component: cytoplasm; endoplasmic reticulum-plasma membrane contact site; cytosol; organelle
Genetic constraint (gnomAD): Loss-of-function variants: 5 observed, 15.96 expected, observed/expected ratio (o/e) 0.31, 90% interval 0.16 to 0.66. The upper end of that interval is the gene's LOEUF score, 0.66, which puts it in group 2 of 6, group 1 being the genes least tolerant of losing a copy. Missense variants: 178 observed, 248.13 expected, observed/expected ratio (o/e) 0.72, 90% interval 0.63 to 0.81. Synonymous variants: 88 observed, 92.93 expected, observed/expected ratio (o/e) 0.95, 90% interval 0.8 to 1.13.
Homologues: Orthologues: chimpanzee PITPNC1 (100% identical), pig PITPNC1 (99% identical), dog PITPNC1 (98% identical), rat Pitpnc1 (96% identical), rabbit PITPNC1 (94% identical), guinea pig PITPNC1 (91% identical), zebrafish PITPNC1 (57% identical). Paralogues in human: PITPNM2 (43% identical), PITPNM1 (42% identical), PITPNA (33% identical), PITPNB (30% identical), PITPNM3 (12% identical).
Diseases named in the same sentence as PITPNC1 in open-access papers:
PITPNC1 is named in the same sentence as 20 diseases in open-access papers, as found by Europe PMC text mining. Sharing a sentence is not in itself a finding about the gene and the disease. The quoted sentences say what the papers report.
gastric cancer (9 papers, 2019 to 2024). A primary or metastatic malignant neoplasm involving the stomach. "Fatty acid metabolic reprogramming mediated by phosphatidylinositol transfer protein, cytoplasmic 1 (PITPNC1) in adipocytes was shown to promote gastric cancer omental metastasis." (PMID 38962317, 2024). "In accordance with previous studies, the regulatory role of phosphatidylinositol transfer protein, cytoplasmic 1 (PITPNC1) in adipocytes and gastric cancer omental metastasis was discovered." (PMID 36428985, 2022). "Two recent studies have examined the role of PITPNC1 in gastric cancer omental metastasis and in radio-resistance in colorectal cancer." (PMID 34111527, 2021). "Gastric cancer cells have elevated levels of PITPNC1 and this is due to the increased levels of cytokines, TNFα and IL6 secreted from adipocytes." (PMID 34111527, 2021). "Several studies indicate that PITPNC1 plays a pro-cancer role; it can promote tumour angiogenesis, metastasis, malignant secretion in breast cancer, omental metastasis of gastric cancer and in the development of radio resistance in colorectal cancer." (PMID 34111527, 2021). "In gastric cancer, phosphatidylinositol transfer protein cytoplasmic 1 (PITPNC1) upregulates the RNA level of PPARG, and PPARγ then enhances the expression of CD36 and mitochondria CPT1 and thereby elevates FA absorption and promotes FAO and metastasis." (PMID 31410189, 2019). "Indeed, elevated levels of phosphatidylinositol transfer protein, cytoplasmic 1 (PITPNC1), in adipocytes are associated with a high prevalence of omental metastasis and with poor prognosis in gastric cancer." (PMID 35053485, 2022). "CPT1b was upregulated by phosphatidylinositol transfer protein cytoplasmic 1 (PITPNC1) to promote FAO and anoikis resistance thus facilitating omental metastasis of gastric cancer." (PMID 35646898, 2022).
breast carcinoma (7 papers, 2017 to 2023). "PITPNC1 functions as a phospholipid transporter that was originally linked to the metastatic phenotype in breast cancer." (PMID 37210549, 2023). "How PITPNC1’s role in pathogenic breast cancer relates to its endogenous function remains unknown." (PMID 30089250, 2018). "PITPNC1 was originally reported as a gene amplified in human breast cancer and over-expressed in breast, colon and melanoma metastasis, where it fosters the pro-metastatic phenotype via secretion of pro-invasive and pro-angiogenic mediators." (PMID 37210549, 2023). "The pathological significance of MAD2L1 in breast cancer; the metastasis promotion of PITPNC1 by melanoma, breast cancer, and colon cancer cells; and the suppression of breast tumors by RIN1 have also been reported." (PMID 33519944, 2021). "PITPNC1 is a reported oncogene in breast cancer, and LINC00910 is a putative oncogenic noncoding RNA." (PMID 34439480, 2021). "It is notable that breast cancer cell-lines have increased levels of PA, a lipid that is bound by PITPNC1 with high affinity." (PMID 34111527, 2021). "Indeed, OCT1 depletion in MCF10CA1a breast cancer cells led to a profound downregulation of PITPNC1 and LINC00910 and exerted anti-cancer effects." (PMID 34439480, 2021). "PITPNC1 was first recognised as a biomarker for human breast cancer metastasis." (PMID 34111527, 2021). "To test whether a decrease in enhancer activating H3K36me3 mark impacts gene transcription, we first assessed gene expression of PITPNC1 and LINC00910 following 9-day treatment of MCF10CA1a breast cancer cells with 7 μM PTS." (PMID 34439480, 2021).
rectal cancer (4 papers, 2022 to 2025). A primary or metastatic malignant neoplasm that affects the rectum. "Subsequent studies characterizing PITPNC1 expression in human specimens revealed its association with advanced clinical stage and poor prognosis in gastric cancer, and with radio-resistance in rectal cancer." (PMID 37210549, 2023). "To further investigate the relevance of PITPNC1 expression levels and radioresistance in rectal cancer, we performed a differential analysis using microarray data from 16 rectal cancer cases (8 radioresistant vs. 8 radiosensitive) from GSE56699." (PMID 38291470, 2024). "Moreover, the overexpression of PITPNC1 seemed to lower the production of reactive oxygen species (ROS), thus increasing the radioresistance in rectal cancer cells." (PMID 35682714, 2022). "In rectal cancer, PITPNC1 can regulate the expression of CD155 via FASN, suppress CD8+ T-cell immune function, and enhance radiation resistance in rectal cancer." (PMID 40217455, 2025). "PITPNC1 regulates the expression of CD155 through FASN, inhibits CD8+ T cell immune function, and promotes radioresistance in rectal cancer." (PMID 38291470, 2024).
colorectal cancer (2 papers, 2021 to 2024). A primary or metastatic malignant neoplasm that affects the colon or rectum. "PITPNC1 is also implicated in resistance to radiotherapy used for therapy for colorectal cancer." (PMID 34111527, 2021). "To further validate the effect of PITPNC1, we used siRNA to knockdown PITPNC1 in radioresistant colorectal cancer cell lines." (PMID 38291470, 2024). "To investigate the key role of PITPNC1/FASN/CD155 in immune regulation, we individually knocked down PITPNC1 and FASN and knocked down PITPNC1 while overexpressing FASN in radioresistant colorectal cancer cell lines." (PMID 38291470, 2024). "In addition, co-culture experiments and in vivo tumor-bearing experiments have shown that silencing PITPNC1 can inhibit FASN/CD155, enhance CD8+ T cell immune function, promote colorectal cancer cell death, and ultimately reduce radioresistance in tumor-bearing models." (PMID 38291470, 2024).
Type 2 diabetes (2 papers, 2018 to 2021). "GWAS studies had identified an expression-associated SNP in PITPNC1 (rs8866) as a risk factor for Type 2 diabetes." (PMID 34111527, 2021).
B cell lymphomas (1 paper, 2023). "MYC suppresses autophagy in B cell lymphomas by antagonizing the function of TFEB transcription factors, raising the possibility that PITPNC1 could control autophagy through MYC in LUAD and PDAC." (PMID 37210549, 2023).
prediabetes (1 paper, 2023). "We observed that the PITPNC1 SNP rs2011941 was associated with TC levels in individuals with prediabetes." (PMID 38371897, 2023).
cancer (13 papers, 2013 to 2025). A tumor composed of atypical neoplastic, often pleomorphic cells that invade other tissues. "PITPNC1 has also been linked to the metastatic progression of several types of cancer, including CRC." (PMID 35682714, 2022). "PITPNC1 is also implicated in cancer metastasis, but in contrast to PITPα and β, has a unique C-terminal extension with two serine phosphorylation sites, which provide docking sites for 14-3-3 protein." (PMID 32039198, 2019). "While further studies should explore this hypothesis, currently there is strong evidence that PITPNC1 is associated with different human cancers." (PMID 32039198, 2019). "We further tested PITPNC1’s clinical role in human cancer by performing survival analysis in LUAD patients." (PMID 37210549, 2023). "Most importantly, PITPNC1 controls a druggable transcriptome that offers opportunities for therapeutic intervention in both cancers." (PMID 37210549, 2023). "Nonetheless, the information about PITPNC1 in cancer is far from being completed, furthermore in the context of dominant oncogenes such as KRAS." (PMID 37210549, 2023). "Given its role in lipid transfer across Golgi membranes, PITPNC1 is mainly thought to affect cancer cell secretion and sustain tumor growth." (PMID 35465326, 2022). "Effectively, PITPNC1 rewires the metabolism of the cancer cells to utilise fatty acids as fuel allowing the cancer cell to metastasise." (PMID 34111527, 2021). "Recent studies identify specific and overlapping functions for the three soluble PITPs (PITPα, PITPβ and PITPNC1) in phospholipase C signalling, neuronal function, membrane trafficking, viral replication and in cancer metastases." (PMID 34111527, 2021). "Recent work has identified that PITPNC1 is over-expressed in multiple cancer types and facilitates Golgi extension and vesicular secretion of pro-tumour factors in these cancer cells." (PMID 29253589, 2018). "Another recent study reported that PITPNC1 drives metastasis of multiple prevalent cancer types by enhancing Rab1B-mediated vesicular secretion of several pro-metastatic genes, which include MMP1." (PMID 28316326, 2017). "In summary, PITPNC1 involvement in cancer is multifactorial." (PMID 34111527, 2021). "Interestingly, many of the DMGs identified had multiple roles and several were potential cancer biomarkers or were previously shown to be implicated in various types of cancers, including ABLIM1, ADAM12, ARHGEF4, FBLN2, ITGA6, LRPAP1, Ly9, NT5E, PITPNC1, PLCG1, OBSCN, RHOH, SPTBN1, SPOCK2 and SPRY1." (PMID 41159936, 2025). "A microRNA (miRNA)-126 that is silenced in a variety of human cancers, regulates the expression of IGFBP2, PITPNC1 and MERTK." (PMID 34111527, 2021). "Studies focused on PITPNC1 have been limited by the lack of pharmacological inhibitors, which precluded exploring its role as a molecular target in cancer or other diseases." (PMID 37210549, 2023). "PITPNC1 has been shown to be overexpressed in metastatic breast, colon, and melanoma cancers, and SMARCA4 is a marker of poor prognosis in many types of cancer." (PMID 34439480, 2021). "Thus, the PITPNC1/RAB1B/GOLPH3/MYO18A/F-actin module participates in anterograde traffic and in some cancers, allows malignant secretion to take place." (PMID 34111527, 2021).
tumor (9 papers, 2017 to 2025). "Given the relevance of concurrent mutations in mut KRAS LUAD prognosis and response to therapy, we explored the association of PITPNC1 expression with prevalently mutated tumour suppressor genes (TSGs)." (PMID 37210549, 2023). "Collectively, these results indicate that PITPNC1 controls the expression of a gene signature with clinical implications for KRAS-mutated tumours." (PMID 37210549, 2023). "If PI4P is increased in the trans Golgi regions, PI4P-binding proteins like GOLPH3 and PITPNC1 are over-recruited, leading to malignant secretion that can develop angiogenesis, tumor invasion, and metastasis." (PMID 39675715, 2025). "Compared to radiosensitive neoplasms, radioresistant neoplasms exhibited significantly higher expression levels of PITPNC1." (PMID 38291470, 2024). "Gene knockdown and rescue experiments demonstrated that PITPNC1 can regulate the expression of CD155 on the surface of tumor cells through FASN." (PMID 38291470, 2024). "Immunohistochemical and immunofluorescence and flow cytometry staining demonstrated that the proportion of CD8+ T cells and IFN-γ+ CD8+ T cells in the tumor tissue increased after silencing PITPNC1 and FASN." (PMID 38291470, 2024). "Simultaneously, examination of the apoptosis rate of tumor cells in the co-culture system indicated an increase in tumor cell apoptosis following the knockdown of PITPNC1 and FASN." (PMID 38291470, 2024). "After subcutaneous tumor irradiation for five treatment cycles, we observed a significant reduction in tumor volume upon silencing of PITPNC1 and FASN." (PMID 38291470, 2024). "To assess alterations in PITPNC1/FASN/CD155 within tumor cells and their direct modulation of CD8+ T cell functionality, we conducted the isolation of individual CD8+ T cells." (PMID 38291470, 2024). "Functional experiments showed PITPNC1 requirement for cell proliferation, cell cycle progression and tumour growth." (PMID 37210549, 2023). "Recently, it has been reported that RAB1B can be recruited by PITPNC1 to the Golgi apparatus, thus promoting the secretion of pro‐invasive and pro‐angiogenic factors and drive several tumor metastases." (PMID 36606322, 2023). "PITPNC1 was also upregulated when compared to normal lung tissue, indirectly suggesting a link to the tumour phenotype." (PMID 37210549, 2023). "Further studies will shed light on the involvement of PITPNC1 in the regulation of Golgi enzymes dynamics and glycosylation process in physiology and in the tumor context." (PMID 35465326, 2022). "PITPNC1 is known to contribute to several oncogenic effects such as tumor angiogenesis, metastasis, and malignant secretion in breast cancer, omental metastasis of gastric cancer and in the development of radio-resistance in colorectal cancer." (PMID 35465326, 2022). "First, PITPNC1 is uncovered as a marker of poor prognosis in both tumour types." (PMID 37210549, 2023). "PITPNC1 knocked-down cells generated tumours of a smaller volume and weight than controls." (PMID 37210549, 2023). "The consistent results across tumours suggest that a PITPNC1-regulated network represents a relevantly common signalling node in KRAS oncogenesis with clinical implications that could be exploited for therapeutic purposes." (PMID 37210549, 2023). "In conclusion, our work uncovers the phospholipid transporter PITPNC1 as a KRAS effector that controls central transcriptional and signalling nodes (i.e. MYC and mTOR) and unveils novel therapeutic strategies for KRAS-driven tumours in the context of a PITPNC1-regulated transcriptional network." (PMID 37210549, 2023). "The investigation revealed that downregulation of PITPNC1 led to apoptosis in radioresistant cells, whereas direct inhibition of FASN indirectly suppressed the expression of CD155 on tumor cell surfaces." (PMID 38291470, 2024).
tumor (continued). "JAK2 inhibitors were predicted as putative PITPNC1 inhibitors with antiproliferative effect and their combination with KRASG12C inhibitors elicited a substantial anti-tumour effect in LUAD and PDAC." (PMID 37210549, 2023). "We also found that transcription factor RUNX1 and gene PITPNC1 were highly expressed along the trajectory to tumor cells but not on the path to more differentiated epithelial cells." (PMID 40470730, 2025). "Upon manipulating the expression of pathway-associated genes in tumor cells and co-cultivating them with CD8+ T cells, we observed that downregulating PITPNC1 and FASN led to an increased proportion of IFN-γ+ CD8+ T cells, along with heightened cytotoxic effects against tumor cells." (PMID 38291470, 2024). "PITPNC1 abrogation in PDAC cells also impaired tumour growth, yielding lighter tumours." (PMID 37210549, 2023).
adenocarcinoma (1 paper, 2009). A common cancer characterized by the presence of malignant glandular cells. "Next, we found Pitpnc1 (phosphatidylinositol transfer protein, cytoplasmic, 1) −12.0-fold down regulated in adenocarcinoma vs transgenic and −14.2-fold down regulated compared with non-transgenic." (PMID 19812696, 2009).
PITPNC1 also shares sentences with these, for which no sentence is quoted: colon cancer (2 papers); melanoma (2); adenoma (1); breast tumors (1); hypopharyngeal cancer (1); Intellectual disability (1); lung adenocarcinoma (1); metastatic tumors (1); pancreatic cancer (1); type 2 diabetes mellitus (1).